CXCL8 (C-X-C motif chemokine ligand 8)
Diseases named in the same sentence as CXCL8 in open-access papers (continued):
Sharing a sentence is not in itself a finding about the gene and the disease.
infection (continued). "Human chemokine C-X-C motif ligand 8 (CXCL8) or mouse functional homolog CXCL2, produced by immune cells, plays an important role in recruiting neutrophils to the sites of infection and inflammation." (PMID 26300888, 2015). "Significant increase in HIV-1p24 was observed with CXCL8 concentration as low as 10 ng/ml, for both HIV-1ADA and HIV-1JRFL infection (p<0.01 and 0.001 respectively)." (PMID 24662979, 2014). "In this context, there is a marked induction of CCL2, CCL3, CCL4, CCL5, CXCL8, and CXCL10 after infection with SIV, as well as a systemic increase of CCL2, CXCL8, and CXCL10 in humans, concurrently with viremia peak after infection with HIV." (PMID 25313360, 2014). "BAL CXCL8/IL‐8 and CXCL1/GRO‐α levels at day 4 post‐infection were correlated with peak nasal lavage virus load (r = 0.721, P = 0.044, and r = 0.738, P = 0.037, respectively) in asthmatics." (PMID 24673807, 2014). "Most were upregulated during infection; however, the greatest increases were in CCL20 (MIP-3α), CXCL1-3 (GROα, β and γ) and CXCL8 (IL-8)." (PMID 24436142, 2014). "Two important chemokines are interleukin 8 (IL8 or CXCL8), a potent recruiter of neutrophils to sites of infection, and chemokine ligand 2 (CCL2), which induces the migration of monocytes from blood to become tissue macrophages." (PMID 25479904, 2014). "We show that both LT and ET impair the production of inflammatory CXCL8, CCL2, CCL3, CCL4, and CCL5 upon infection, whereas the recruitment of PMN is significantly inhibited by LT only." (PMID 22937027, 2012). "Compared with medium control, mycobacterial infection of neutrophils and monocytes induced an ascendant CXCL8 and CCL2 secretion that peaked 3 h after infection." (PMID 22058091, 2012). "The interaction of the two cell types leads to the rapid release of the pro-inflammatory mediators CXCL8 and TNF-α into the microenvironment, thereby potentially maintaining neutrophil influx at the site of infection." (PMID 21589907, 2011). "MCP3 and CXCL5 showed increases only late in the infection process, while CXCL8 (IL-8) showed increased transcription early in the infection then decayed to noninfected levels." (PMID 22331987, 2010). "T-cells produce a broad range of pro- and anti-inflammatory cytokines, including IL-2, IL-6, CXCL8, TNF and IL-10, in response to infections or other stress factors." (PMID 20507572, 2010). "Virally, stimulatedpDC produces chemokines, such as CCL3 (MIP-1a), CCL4 (MIP-1b), CCL5 (RANTES),CXCL8 (IL-8), and CXCL10 (IP-10) which stimulate Th1, and NK cells homing tosite of infection through IP-10 and CCL4, respectively." (PMID 19190769, 2008). "CXCL8 production by fibroblasts is potently induced by IL-1β, TNF-α, and bacterial products, positioning fibroblasts as key regulators of neutrophil recruitment in response to infection or tissue damage." (PMID 41598494, 2026). "CXCL8 (initially interleukin-8 [IL-8]), a member of the CXC chemokine family, is a potent, selective neutrophil chemoattractant produced by macrophages, epithelial cells, and endothelial cells in response to inflammation and infection." (PMID 40718478, 2025). "ELISA of the supernatant after infection or combined treatment showed that Pg infection promoted the secretion of CXCL1 and CXCL8 proteins by HOKs, and acetylcholine exacerbated this process, further enhancing CXCL1 and CXCL8 secretions." (PMID 41358003, 2025). "Furthermore, Andrographolide significantly diminishes the release of pro-inflammatory cytokines such as IL-6, C-X-C motif chemokine ligand 8 (CXCL-8), and interferon-gamma- IP-10 by epithelial cells triggered by the infection." (PMID 40276605, 2025). "IL-8/CXCL8 can be produced by various cell types, including fibroblasts and endothelial cells, and is mainly known as a chemoattractant for neutrophils, playing an important role in the response to infection and tissue damage." (PMID 40061210, 2025).
infection (continued). "Surprisingly, compared to uninfected HIBCPP cells, infection with C. albicans did not alter the secretion of CXCL8, CCL2, and CCL5 after 24 h, respectively, which was the fact for both the basolateral (blood) and apical (CSF) side." (PMID 40181464, 2025). "CXCL8 plays a key role in the body’s response to infection—it not only attracts neutrophils, but also helps them release enzymes and reactive oxygen molecules to fight off harmful agents." (PMID 40943634, 2025). "As expected, the data revealed greater accumulation of secreted CXCL8 during EV-D68 infection than in the noninfected groups." (PMID 39962077, 2025). "Histological findings of immune cell infiltration in tracheal tissues after infection with swH1N1 was in line with induction of cytokines and chemotactic factors (AMCF-II, CXCL8/IL8, CXCL2, CXCL10, and CCL20) as well as receptors (CCR1 and CXCR2) in lower trachea after this infection." (PMID 39247193, 2024). "During the acute febrile phase of infection, patients with DHF and DWC exhibitedelevated CXCL-8 (p-value < 0.01) comparedwith those with DF.Furthermore, patients with DHF and DWC exhibited increased CXCL-10 serum levels(p-value < 0.01) compared to those with DF." (PMID 39082520, 2024). "Though not historically considered major cytokine producers, neutrophils do also produce a range of cytokines and chemokines, such as TNF, IL-1β, IFNγ, IL-4, IL-10, IL-13, IL-17, CXCL8, and CXCL9/10, which contribute to shaping the inflammatory response to infection." (PMID 39015565, 2024). "Similarly, PGE2 can also promote the synthesis of CXCL8/IL8, which is crucial for attracting neutrophils to sites of infection or inflammation." (PMID 39769290, 2024). "Compared to the medium, UV-inactivated RV16, filtered RV16, and the non-virus 0.1% DMSO infection medium did not significantly induce IL-6, CXCL8, or CCL5 protein release." (PMID 39598462, 2024). "We can therefore hypothesize that the CXCL8 and CCL20 differential responses after infection could be attributed to a differential intracellular fate of Salmonella in ileal and caecal chicken epithelial cells." (PMID 37525204, 2023). "However, this seemed to be a transient phenomenon, as the expression of CXCL8 and CXCL6 was significantly increased at 12 h post-infection (last time measured)." (PMID 38133333, 2023). "Upregulation of genes such as CXCL8 (platelet cytokine) and TNFSF10 (apoptosis mediator) in HVR at an early stage of infection might act as pointers of a severe disease course." (PMID 37644081, 2023). "Consistent with SARS-CoV-2 infection of human airway epithelial cells, we observe a rapid proinflammatory response during the early stages (24 h) of infection characterized by an increased expression of multiple cytokines and chemokines (e.g., CCL20, IL-6, CXCL8 and CXCL10)." (PMID 37112842, 2023). "Baseline (medium-treated) BAL cells from obese individuals had significantly reduced spontaneous and post-infection production of IL-6, CXCL8/IL-8 and TNF compared to non-obese individuals." (PMID 37857661, 2023). "We conclude that IFNA1, IRF3, CXCL8, CXCL10, IFNB1, and CHUK are the key hub genes involved in the H5N1 human infection, which makes a major contribution towards the inflammation or cytokine storm leading to the prognosis of the disease and critical clinical outcomes." (PMID 37515084, 2023). "In infections with regular vegetative cells, the IL-6 and TNF-α inflammatory response continued to increase in the first 1.5 h, remaining constant at 24 h, while CXCL-8 decreased by 24 h." (PMID 36920189, 2023). "Infection with both ZIKV lineages was characterized by a more proinflammatory and chemotactic profile, mediated by high levels of IL-1β, IL-6, TNF-α, CCL-2, CCL-3, CCL-7, CXCL8, IP-10, and VEGF." (PMID 37227282, 2023). "As CXCL8, CXCL10, and EGF are hub genes in the infection process, studies on these genes might promote the development of SARS-CoV-2 research." (PMID 37196111, 2023).
infection (continued). "Using alternative WNV models of infection that have an ortholog CXCL8 gene, such as rabbits and nonhuman primates, will be necessary to circumvent this issue." (PMID 36992514, 2023). "To determine whether this model elicits a pro-inflammatory response, similar to what has been shown previously using shorter infection times, we analyzed mRNA expression levels of IL-1β, IL-6 and CXCL8 (IL-8) along with protein levels of IL-8 in our model." (PMID 37432929, 2023). "CXCL8, released by endothelial cells, and CXCR2 also play a key role in neutrophil attraction in sepsis, a potentially life-threatening condition characterized by an extreme response of the body to infection resulting in injury to its own tissues." (PMID 36725964, 2023). "In addition, serine proteases can prevent the chemoattraction of phagocytes by depredating the chemokines (Chemokine (C-Cmotif) ligand 5, CCL5 and C-X-C motif chemokine ligand 8, CXCL8) at the infection site." (PMID 37990198, 2023). "For example, alternative infection models should be developed for the study of CXCL8, hampered to date by the lack of true homologs in rats and mice." (PMID 36992514, 2023). "In skin diseases, it has been found that the interaction CXCL8/ACKR1 between macrophages and endothelial cells is enhanced, and the purpose of this interaction is to recruit immune cells to inflammatory sites in order to fight the infection." (PMID 37207221, 2023). "Additionally, RGS2 expression was strongly correlated with PTGS2, IL1B, CXCL8, NAMPT and other inflammation markers with substantial upregulation in early infection." (PMID 36143181, 2022). "In addition, ASFV-ΔH240R infection induced higher expression of proinflammatory cytokines, including IL-1β, IL-6, TNF-α, and C-X-C motif chemokine ligand 8, in PAMs than did ASFV-WT infection." (PMID 36326277, 2022). "During this process, the chemokine CXC Ligand 8 (CXCL8) - Chemokine CXC receptor 2 (CXCR2, also known as IL-8RB, IL-8R2, IL-8Rβ) axis facilitates migration and secretion of inflammatory mediators critically in both the early and late phases of infection." (PMID 36451225, 2022). "Median values of hBD-2 (V = 90, P < 0.001), RNase 7 (V = 286, P > 0.05), IL-1β (V = 749, P > 0.05) and IL-8 (CXCL-8) (V = 413, P < 0.001) increased during infection, but not for IL-6." (PMID 36382385, 2022). "In contrast, a non-ribosomal gene CXCL8 had increases in both poly(A) length and expression level after infection, which suggested that this correlation belonged exclusively to the ribosomal protein genes." (PMID 35464437, 2022). "Finally, a high number of pro-inflammatory cytokines were up-regulated upon infection, such as CXCL10, CCL5, CXCL11, TNF, CCL3, CXCL8, and IL6." (PMID 35893684, 2022). "The S. pyogenes CEP (SpyCEP) was originally identified by its ability to cleave human CXCL8, after it was noted that lethal necrotizing GAS infections were characterized by poor neutrophil recruitment to sites of infection despite the significant bacterial burden." (PMID 34649250, 2022). "Notably, the NOD-like receptor proteins NOD1 and NOD2 can participate in innate immune responses, and NOD1 stimulates the release of chemokines, such as CXCL-8, CXCL-1, and CXCL-2, which can attract neutrophils to the site of infection." (PMID 35993024, 2022). "Our past studies of adenovirus infection of human corneal fibroblasts in vitro and in a mouse model of adenovirus keratitis in vivo showed early expression of CXCL8 and its murine homologue CXCL1, respectively; and CCL2, and ICAM-1, all within the first day post infection (pi)." (PMID 34960773, 2021). "Optimisation of Pa infection of BEAS-2B cells identified that a bacterial concentration of 2.5 x 107 PFU/ml significantly induced IL-6 release with little cell death and an incubation period of four hours was optimal for both IL-6 and CXCL8 measurement." (PMID 33524056, 2021).
infection (continued). "CXCL8 and MPO levels in the peripheral blood do not differ with infection status nor associate with birth outcomes." (PMID 34737733, 2021). "However, upon comparing the chemokine profile of the three hCoVs, it can be concluded that CCL2/MCP-1, CXCL8, and CXCL10/IP10 have vital roles in the pathogenesis of infection and serve as prognostic markers for hCoVs’ severity." (PMID 34046036, 2021). "The increased release of TNF-α, IL-23, CCL2, CXCL8, and CXCL10 by sc1o-treated MdMs may contribute to a pro-inflammatory environment at the infection site and thereby promote the immune response against pathogens via several mechanisms." (PMID 33330947, 2021). "No significant change was observed for CXCL8 mRNA levels upon LF pre-infection treatment (washed), whereas pre-infection treatment (unwashed) significantly upregulated it, as compared to infected untreated control." (PMID 33498631, 2021). "UDP-mediated activation of P2Y6 receptor promotes the recruitment of inflammatory cells to sites of inflammation or infection by inducing the production of various chemokines including CCL2 (monocyte chemotactic protein 1, MCP-1), CXCL8 (IL-8) and CCL20 (macrophage inflammatory protein-3α, MIP-3α)." (PMID 34064383, 2021). "Upon experimental infection with L. major, macrophage inflammatory protein (MIP)-2 and keratinocyte-derived cytokine (KC; also known as CXCL1), the functional murine homologues of human CXCL8 are rapidly produced in the skin." (PMID 34832536, 2021). "In addition, the 040417 strain reduced the production of CXCL8 at the two times points evaluated and diminished the levels of CCL5 and CXCL10 at hour 72 post-infection." (PMID 34064210, 2021). "This synergy, as well as the potent inhibition of both IL-6 and CXCL8 by an NSKI, suggest that targeting a few select kinases may be a potential new mechanism for anti-inflammatory therapy in the context of Pa infections in CF and other patients." (PMID 33524056, 2021). "In addition, we discovered that ASFV infection is involved in the regulation of chemokine expression in PAMs, and the chemokines, such as C-X-C motif chemokine 8 (CXCL8) and CXCL10, were upregulated after infection." (PMID 34412678, 2021). "Since CXCL-8, IL-1β and TNF-α resulted as statistically significant overexpressed cytokines after 2h post infection, we analyzed their concentration at a protein level in supernatants of neutrophils infected with A. baumannii ATCC® 19606TM also 4 h after infection." (PMID 33253325, 2020). "Further, in vitro infection of human type II alveolar epithelial cells maintained at an air-liquid interface led to productive virus replication and significant upregulation of CXCL10 and CXCL11, as well as CXCL8 and the Th1 cell-directed chemokine CCL5." (PMID 33613280, 2020). "Furthermore, we verified the upregulation of CXCL8, CXCL2, CXCL3, IFNλ-1, -2 and IFIT-2 genes following an apical infection of HIBCPP cells with E-30 at MOI 20 compared to uninfected condition." (PMID 32872518, 2020). "Interestingly, among the unique upregulated genes upon apical infection of HIBCPP cells, we noted CXCL1, CXCL8 and IL-6." (PMID 32872518, 2020). "During these infections, the transcription of IFN-γ was highly correlated to the bacterial and viral load in both spleen and kidney together with a strong correlation to the expression of an array of CXC chemokines, including CXCL8 or IL-8." (PMID 33172079, 2020). "Additionally, in a study in vitro using a WT hRSV A2 strain (6340WT) and a recombinant strain that lacks the G-protein gene (6340ΔG), infection of NHBEs cells induced the secretion of CCL2, CCL5, and CXCL8 by both viruses." (PMID 30936869, 2019). "Chemokines such as CXCL8 and CXCL13 can recruit immune cells to the site of infection." (PMID 31656701, 2019). "However, we found that the expression of CXCL8, MMP3, and MUC5AC was higher in the MG-infection group compared to the E. coli-infection group." (PMID 31803158, 2019).
infection (continued). "Similar to airway epithelial cells, human macrophages express type I and type III IFNs, IL-1α, IL-1β, IL-6, TNF-α, CXCL8, CCL2 (MCP-1), CCL3 (MIP-1α), CCL4 (MIP1-β), CXCL9, and CXCL10 following infection with seasonal H1N1 or with H5N1, 2009 H1N1 strains demonstrating increased pathogenicity." (PMID 29623073, 2018). "We report a strong induction of numerous pro-inflammatory cytokines, chemokines and AMPs such as CXCL1, CXCL2, CXCL5, CXCL8, CCL20, TNFα, TSLP, IL-23α, IL-32, IL-6, hBD2 and S100A7 during the infection of monolayered primary keratinocytes and reconstructed epidermis with the wild-type PAK strain." (PMID 30070169, 2018). "By contrast, pathogens cause epithelial cells to release proinflammatory factors, such as IL-8 (CXCL-8), MCP-1 (CCL2) and MIP-3α and might trigger rapid response to clear the infection." (PMID 29896198, 2018). "RT-qPCR analysis of the expression of key components of the host innate immune response to infection, such as the chemokines/cytokines CCL20, CXCL8, TNF-α, the two β-defensins, LAP and TAP and the acute phase protein SAA3, confirmed the different abilities of R- and S-LPS to stimulate PS cells." (PMID 30142177, 2018). "IL-8, also known as CXCL8, is a potent pro-inflammatory chemokine whose primary function is to recruit and activate inflammatory cells, mainly neutrophils, to the site of infection via a chemotactic gradient." (PMID 29101248, 2017). "Previous studies have demonstrated that the amount of RSV strain A used to infect human epithelial kidney cells directly correlated with the level of CXCL8/IL-8 and RANTES produced in response to infection, and chemokine production in response to infection was dependent on TLR3 expression." (PMID 26732674, 2016). "Consistent with our previous observations in ovine trophoblasts, only active infection, but not exposure to UV-killed organisms, stimulated CXCL8 release." (PMID 27002636, 2016). "In our analysis, we observe that a subset of these cytokines reported to be present in the serum also show transcriptional upregulations in PBMCs by 4 days post-infection (IL6, IL1B, IL1RN, CCL8, CXCL10) and by 7 days post-infection (CCL2, CCL3, CSF1, TNF, CXCL1, FAS and CXCL8)." (PMID 27595844, 2016). "CXCL8 release was significantly elevated in each of the cell lines by active-infection with live W. chondrophila, but not by exposure to UV-killed organisms." (PMID 27002636, 2016). "Through induction of IL-6 as well as chemokines such as CCL2, CXCL8, and CXCL10, Vγ9/Vδ2 T cells and MAIT cells are likely to enhance local inflammation and contribute to further recruitment of monocytes, neutrophils, and lymphocytes to the site of infection." (PMID 27527598, 2016). "While CXCL8 levels were increasing over time, the maximum of HMGB1 was reached already at 8 hours post-infection, indicating that the cell and tissue injury occurs at the early stage of infection." (PMID 26601609, 2015). "Neutrophils that are primarily recruited by CXCL8 can exert antiviral immunity amongst others by the release of inflammatory cytokines (e.g., IL-12, TNFα) and chemokines (e.g., CCL2, CXCL8, CXCL9, CXCL10) that leads to further recruitment of immune cells to the site of infection." (PMID 24646914, 2014). "To determine whether HIV-1-infected MDM secreted CXCL8, we first measured levels in culture supernatants following HIV-1ADA or HIV-1JRFL infection at different time points." (PMID 24662979, 2014). "LY294002 potently inhibited CXCL8 and CCL5 production in response to infection with RV-1B or RV-16." (PMID 25541728, 2014). "During an infectious insult in the liver, resident macrophages and dendritic cells detect the presence of invading pathogens (via PRRs/PAMPs mechanisms) and will release chemokines CXCL8 (IL-8), CXCL1, 2, 3, CCL2, 3, 4 to attract neutrophils and monocytes at the site of infection." (PMID 22933833, 2012).